FGF2 (fibroblast growth factor 2)
Diseases named in the same sentence as FGF2 in open-access papers (continued):
Sharing a sentence is not in itself a finding about the gene and the disease.
ovarian carcinoma (46 papers, 2004 to 2025). A malignant neoplasm originating from the surface ovarian epithelium. "Taken together, these results demonstrate that E-cadherin acts as a crucial suppressor of ovarian cancer invasiveness, and along with other described mechanisms, the loss of E-cadherin plays an important role in FGF2-induced cell invasion." (PMID 23554977, 2013). "In ovarian cancer cells, it has been demonstrated that fibroblast growth factor (FGF2) results in increased expression of SLUG and ZEB1 by activating the PI3K/AKT/mTOR and MAPK/ERK signaling pathways." (PMID 40678416, 2025). "Another approach was the use of polyethylene glycol as an adapter linking AdVs to fibroblast growth factor 2 (FGF2) to improve the tropism of vectors to ovarian cancer cells." (PMID 39596526, 2024). "Compared with normal ovarian tissues, the expression of FGF2 in ovarian cancer tissues was significantly increased, and negatively correlated with the overall survival time of patients with ovarian cancer." (PMID 36059652, 2022). "It has been reported that high-molecular-weight forms of FGF2 play a radioprotective role in ovarian cancer cells." (PMID 34127812, 2021). "FGF2 is a potent angiogenic molecule involved in tumour progression, and is one of several growth factors with a central role in ovarian cancer." (PMID 33573134, 2021). "As a first step toward analyzing the role of FGF2 in ovarian cancer progression, we investigated the effect of FGF2 on E-cadherin expression in OVCAR-4 and SKOV-3 cells." (PMID 23554977, 2013). "In contrast, previous in vitro studies and the gene expression profiling of advanced ovarian cancer suggest that FGF2 acts as an autocrine growth factor for ovarian cancer cell proliferation and invasion." (PMID 23554977, 2013). "Several in vitro studies and the gene expression profiling studies in advanced ovarian cancer reveal that FGF2 functions as an autocrine growth factor for ovarian cancer cell proliferation, and invasion." (PMID 23554977, 2013). "The present study shows that FGF2 induced the down-regulation of E-cadherin expression, which is involved in FGF2-induced ovarian cancer cell invasion." (PMID 23554977, 2013). "The biological significance of E-cadherin reduction in ovarian cancer invasiveness was demonstrated by the fact that overexpression of E-cadherin blocked FGF2-induced cell invasion in vitro." (PMID 23554977, 2013). "Clinical studies have shown a high levels of FGF2 and its mRNA in advanced primary ovarian cancers when compared to normal ovaries." (PMID 23554977, 2013). "The current data support a crucial role for FGF2 in the down-regulation of E-cadherin in ovarian carcinoma cells via the PI3K/Akt/mTOR and MAPK/ERK signaling pathways." (PMID 23554977, 2013). "Fibroblast growth factor 2 (FGF2) is produced by ovarian cancer cells and it has been suggested to play an important role in tumor progression." (PMID 23554977, 2013). "Taken together, these results indicate that the MAPK/ERK and PI3K/Akt/mTOR pathways are involved in FGF2-induced ovarian cancer cell invasion." (PMID 23554977, 2013). "Fibroblast growth factor-2 (FGF2) mediates various cellular events, including proliferation, motility, and differentiation, and malignant ovarian tumors are common in patients with elevated FGF2." (PMID 23554977, 2013). "The elevated levels of FGF2 and its receptors present in ovarian malignant tumors suggest that FGF2 plays an important role in ovarian tumor progression." (PMID 23554977, 2013). "ALDH1A3, FGF2, and IL-6 have emerged as therapeutic targets for ovarian cancer." (PMID 40507922, 2025). "The results of studies in patients with ovarian cancer show that FGF2 is one of several growth factors that play a core role in the carcinogenesis of ovarian cancer, and it is also the main angiogenic factor expressed in ovarian cancer at mRNA level." (PMID 36059652, 2022).
ovarian carcinoma (continued). "In addition, the present study suggests that the down-regulation of E-cadherin mediates FGF2-induced ovarian cancer cell invasion." (PMID 23554977, 2013). "Finally, our results indicate that the down-regulation of E-cadherin-mediated FGF2 enhances the invasiveness in ovarian cancer cells." (PMID 23554977, 2013). "Thus, we examined the effect of FGF2 on cell invasion in ovarian cancer cells using Matrigel-coated Transwell invasion assays." (PMID 23554977, 2013). "In addition, our studies suggest that FGF2 exerts its effects in human ovarian cancer cells via the activation of the PI3K/Akt/mTOR and MAPK/ERK signaling pathways and the subsequent increased expression of Slug and ZEB1." (PMID 23554977, 2013). "Similarly, Western blot analysis showed that treatment with FGF2 down-regulated E-cadherin protein levels in a dose-dependent manner in ovarian cancer cells." (PMID 23554977, 2013). "Finally, FGF2-induced cell invasion was abolished by the inhibition of the PI3K/Akt/mTOR and MAPK/ERK pathways, and the forced expression of E-cadherin diminished the intrinsic invasiveness of ovarian cancer cells as well as the FGF2-induced cell invasion." (PMID 23554977, 2013). "In addition, we also found that overexpression of BTN3A3 could reduce the protein level of FGF2 in the nucleus of ovarian cancer cell line 3AO." (PMID 36059652, 2022). "Interestingly, interactions between DLX4 and bFGF/FGF2 have been reported in ovarian cancer tissue." (PMID 34834487, 2021). "Thus, the results of this study indicated that EGFL6 could regulate cell proliferation, migration, and angiogenesis in ovarian cancer cells by regulating the FGF-2/PDGFB signaling pathway." (PMID 32983976, 2020). "Moreover, rapamycin treatment significantly increased the protein levels of E-cadherin and markedly diminished the suppressive effect of FGF2 on E-cadherin protein levels, indicating that the PI3K/Akt/mTOR pathway is involved in FGF2-induced E-cadherin suppression in ovarian cancer cells." (PMID 23554977, 2013). "However, the role of FGF2 in ovarian cancer progression is still controversial." (PMID 23554977, 2013). "Also, several studies have shown increased plasma levels of FGF2 in ovarian cancer patients." (PMID 23554977, 2013). "Overexpression ABCB1, FGF2, CXCR4, and IL6 portends aggressive ovarian cancer behaviors and poor prognoses." (PMID 40507922, 2025). "ALDH1 is commonly used as a marker of ovarian cancer stem cells, and ALDH1A3 and FGF2 within the microenvironment preserve the stemness of cancer stem cells." (PMID 40507922, 2025). "Secondly, the top six genes, each with more than 100 publications (KIT, EGF, STAR, GAL, FGF2, VIP), have known established roles in ovarian cancer." (PMID 40699804, 2025). "It is interesting to note that the PDX-intrinsic cytokines produced by ovarian cancer huPDX models are distinct from those produced by other cancer models producing high levels of IL-8, M-CSF, IP-10, MCP-1, VEGF-A, FGF-2, and PDGF-AA." (PMID 36860657, 2023). "In breast and ovarian cancers, SULF1 exhibition of a tumor suppressive effect was relevant to its ability to attenuate FGF2, HB-EGF, and amphiregulin signaling." (PMID 28525382, 2017). "Fibroblast growth factor 2 (FGF2), which is a member of the FGF family, induces ovarian cancer cell invasion by the activation of the PI3K/Akt/mammalian target Of rapamycin (mTOR) and MAPK/extracellular signal-regulated kinase (ERK) signaling pathways." (PMID 26356073, 2015). "In this study, we report that FGF2 treatment down-regulated E-cadherin by up-regulating its transcriptional repressors, Slug and ZEB1, in human ovarian cancer cells." (PMID 23554977, 2013). "Taken together, our findings indicate that FGF2 differentially regulates Slug and ZEB1 expression via the PI3K/Akt/mTOR and MAPK/ERK signaling pathways in human ovarian cancer cells." (PMID 23554977, 2013).
ovarian carcinoma (continued). "This study demonstrates a novel mechanism in which FGF2 down-regulates E-cadherin expression through the activation of PI3K/Akt/mTOR and MAPK/ERK signaling, and the up-regulation of Slug and ZEB1 in human ovarian cancer cells." (PMID 23554977, 2013). "Overexpression of E-cadherin decreased basal invasiveness and abolished the ability of FGF2 to induce ovarian cancer cell invasion, implicating that E-cadherin plays an essential role in FGF-stimulated ovarian cancer cell invasion." (PMID 23554977, 2013). "Taken together, our results indicate that the FGF2-dependent PI3K/Akt/mTOR and MAPK/ERK activation is involved in FGF2-induced E-cadherin down-regulation and cell invasion in ovarian cancer cells." (PMID 23554977, 2013). "In vivo, in the chick embryo allantoic membrane (CAM) assay, aplidine inhibited spontaneous angiogenesis, angiogenesis elicited by exogenous VEGF and FGF-2, and induced by VEGF overexpressing 1A9 ovarian carcinoma cells." (PMID 15173857, 2004). "BTN3A3 can bind to FGF2, regulate the protein level of FGF2, and then regulate the phosphorylation level of ERK1/2, thus affecting the proliferation, migration and invasion of ovarian cancer cells." (PMID 36059652, 2022). "Several studies demonstrated that CPXM2, FGF2 and NOVA1 might be available biomarkers for cancers such as hepatocellular carcinoma (HCC), ovarian cancer (OC) and non-small cell lung cancer." (PMID 34559577, 2021). "FGF2, which is a member of the FGF family, normally presents in plasma at a concentration less than 10 pg/ml, and elevated levels (up to 6 ng/ml) can be found in ascetic fluid from ovarian cancer patients." (PMID 23554977, 2013).
pancreatic cancer (46 papers, 1995 to 2025). "A recent study in pancreatic cancer, miRNA-203-3p has been indicated to suppress the invasion and migration of tumor cells via downregulating FGF2." (PMID 37980162, 2023). "A study reported that fibroblast growth factor-2 (FGF-2), secreted by cancer-associated fibroblasts, stimulates CXCL8 release and results in pancreatic tumor progression." (PMID 36612163, 2022). "It has been reported that the deletion of FGF2 in nucleus of pancreatic stellate cells significantly inhibits the invasive ability of pancreatic cancer cells." (PMID 36059652, 2022). "The authors presented that the FGF2-growth factor-induced shedding of syndecan-1 from the cell membrane makes the mitogenic response of pancreatic cancer cells glypican-1 dependent, which in turn cannot be compensated for by syndecan-1." (PMID 33742285, 2021). "Our findings are in line with previous studies, pointing on the relevance of CAFs and CAF-released factors, such as FGF2, in establishing a more aggressive behaviors in pancreatic cancer cells." (PMID 34638477, 2021). "These cellular components can promote desmoplasia in the pancreatic cancer microenvironment through the secretion of certain molecules, such as TGFβ, fibroblast growth factor 2 (FGF2), and connective tissue growth factor (CTGF)." (PMID 30060755, 2018). "We demonstrated that miR-497 plays a role in modulating the malignant phenotype and chemosensitivity of pancreatic cancer cells by directly inhibition of FGF2 and FGFR1 expression." (PMID 25149530, 2014). "Basic FGF (FGF-2) is an FGF family member that is significantly overexpressed in human pancreatic carcinoma." (PMID 24212642, 2011). "This is also indirectly supported by the observation that FGF2 and Shh, which are known to increase pancreatic cancer cell growth and invasion, led to reduction of Runx2 mRNA expression in Panc-1 pancreatic cancer cells." (PMID 17876328, 2007). "Expression of Hsulf-1 in Panc-1 cells negatively influences growth and invasion by attenuating FGF-2 signaling, suggesting that Hsulf-1 plays a specific role in the pathogenesis of pancreatic cancer." (PMID 15817123, 2005). "Based on data that has attributed cellular functions to fibroblast proliferation in other tissues, we investigated a panel of ten central regulators of cell proliferation (c-Myc, Cyclin D1, Cyclin E1, FGF2, FGFR2, EGFR, EGF, FGF1, FGFR1 and VEGFA) in pancreatic cancer-associated fibroblasts (CAFs)." (PMID 38678032, 2024). "Hsulf-1 expression in Panc-1 cells also partially blocked FGF-2 induced MAPK phosphorylation and invasion, further supporting the hypothesis that Hsulf-1 interferes with FGF-2 signaling in pancreatic cancer cells." (PMID 15817123, 2005). "This suggests that, whilst the other ligands were retained intracellularly, FGF2 might be a critical driver for promoting cancer progression by affecting cancer cells via autocrine or, in tumor microenvironments, via paracrine signaling similar to that described in pancreatic cancer." (PMID 40076427, 2025). "KCMF1, a potassium channel regulatory factor, promotes the development of pancreatic cancer by modulating MAPK levels and driving cell proliferation, and it is also elevated in gastric cancer via FGF2 signaling pathway." (PMID 39661479, 2025). "In pancreatic cancer cell lines, GPC1 plays a key role in the mitogenic stimuli provided by fibroblast growth factor 2 (FGF2) and heparin-binding EGF-like growth factor (HB-EGF)." (PMID 36142190, 2022). "The HPA/syndecan-1 axis promotes the upregulation of FGF2, which in turn activates the PI3K/Akt pathway and EMT in cultured pancreatic cancer cell lines." (PMID 33669066, 2021). "More precisely this has been shown for GPC1 in pancreatic cancer cells, where syndecan-1 and GPC1 are both required for FGF2-growth factor response leading to metastasis and shedding of GPC1 cannot be compensated for by higher levels of SDC1." (PMID 33742285, 2021).
pancreatic cancer (continued). "The FGFR1 IIIb induced cell proliferation after FGF‐1, FGF‐2 and FGF‐4 stimulations via production of a glycosylated 110kd protein in pancreatic cancer cells." (PMID 30945363, 2019). "Another study using an organotypic model of PDAC showed that nuclear translocation of fibroblast growth factor 2 (FGF2) and fibroblast growth factor receptor 1 (FGFR1) in PSCs drives invasion of both PSCs and pancreatic cancer cells into the surrounding ECM." (PMID 29903049, 2018). "A HS mimetic M402 currently in Phase I/II trials in pancreatic cancer was designed to inhibit tumor-host interactions including VEGF, FGF2, SDF-1 and heparanase." (PMID 25669977, 2015). "Aspc-1, Capan-1, Panc-1 and T3M4 pancreatic cancer cells were treated with recombinant TGF-β1, BMP2, FGF2, Shh, Ihh and TNF-α for 48 h." (PMID 18163903, 2007). "It has been shown previously that a variety of growth factors such as FGF-2, EGF, HB-EGF, and IGF-1 are over expressed in pancreatic cancer and that they have the potential to act as mitogens for pancreatic cancer cell lines." (PMID 15817123, 2005). "Interestingly, the pro-angiogenic effect of FGF-1 and FGF-2 besides the VEGF–VEGFR2 axis was already demonstrated and combination of the pan-FGFR inhibitor SSR128129E with DC101 in mouse models of pancreatic cancer yielded an additive therapeutic effect." (PMID 28814715, 2017). "At the invasive front of human pancreatic cancer, FGF2 and FGFR1 localise to the nucleus in activated PSCs but not cancer cells." (PMID 24503018, 2014). "Though the regulation of FGF2 and FGFR2 on SOX2 has been already reported in the development phase, we were the first to demonstrate that FGFR signaling regulates the protein stability of SOX2 through AKT and promotes its nuclear localization, thus enhancing stemness in pancreatic cancer." (PMID 32457900, 2020). "However, the fact that HPA, FGF2, and MMP7 are all upregulated in PDAC tissue samples makes it reasonable to assume that syndecan-1 shedding could also be happening during pancreatic cancer progression." (PMID 33669066, 2021). "Interestingly, all but 3 (FGF-2, RANTES and IL1β) of the 23 mediators that emerged as significant when comparing pancreatic cancer to nonmalignant tissue also emerged as significant when comparing pancreatic cancer to pancreatitis." (PMID 26498838, 2015). "Finally, we developed stroma-rich 3D heterospheroids of pancreatic tumor cells (PANC-1) and hPSCs as a model representing fibrotic tumor stroma and examined the efficacy of FGF2-SPIONs with or without chemotherapy on the tumor spheroid growth with or without the presence of external magnetic field." (PMID 31911892, 2020).